STAT3 (signal transducer and activator of transcription 3)
Diseases named in the same sentence as STAT3 in open-access papers (continued):
Sharing a sentence is not in itself a finding about the gene and the disease.
tumor (continued). "For example, unphosphorylated STAT31 can control the architecture of the chromatin, and acetylated STAT3 can contribute to the DNA methylation that silences tumor-suppressor genes." (PMID 38397437, 2024). "Downregulation of PKM2 expression by lapatinib-mediated EGFR and HER2 suppression decreases STAT3 and phosphorylated STAT3 expression, resulting in decreased gene transcription and prevention of tumor cell proliferation." (PMID 39411137, 2024). "The NEAT1 (a long noncoding RNA) participates in invasion, chemoresistance in EC cells, and remodeling tumor microenvironment by induced miR-361 suppression, which activates STAT3." (PMID 39188680, 2024). "For example, STAT3-IN-1 dual-inhibition of the acetylation and phosphorylation of STAT3, displays a potent tumor inhibitory effect in pre-clinical models." (PMID 38245798, 2024). "Other non-malignant cells in the surrounding area can also have increased STAT3 activation since STAT3 can become activated in the tumor microenvironment in part due to the presence of cytokines that activate this protein, like IL-6." (PMID 38611065, 2024). "Abnormal activation of the JNK/STAT3 signaling pathway has been observed in multiple types of tumors, promoting tumor proliferation and angiogenesis." (PMID 38724606, 2024). "Triptolide can exert anti-tumor effects on lung carcinoma cells of NSCLC by inhibiting the activation of the IL-6/STAT3 axis." (PMID 38361933, 2024). "On the other hand, studies have confirmed that lncRNA-p21 binding to STAT3 inhibits the phosphorylation of STAT3, thereby decreasing its stability, ultimately significantly inhibiting tumor cell proliferation and promoting apoptosis." (PMID 38172648, 2024). "The just‐mentioned immunosuppressive mechanism in the tumor microenvironment is supported by an autoinflammatory loop regulated via the IL‐1β/IL‐6/signal transducer and activator of transcription 3 (STAT3) axis." (PMID 38775220, 2024). "Lastly, STAT3, a transcription factor that regulates downstream signals for cell proliferation and apoptosis, has been found to promote tumor cell growth through PTX3." (PMID 39594709, 2024). "Wnt2 can inhibit the anti-tumor effects mediated by dendritic cells through the SOCS3/p-JAK2/p-STAT3 pathway." (PMID 39598398, 2024). "Consistent with gene expression analysis and immunohistochemical staining, immunoblot analysis revealed that p-STAT3, p-P65, Bcl-2, Bcl-xL and cyclin D1 levels in tumor tissues from KI mice were dramatically increased." (PMID 38607004, 2024). "Either inhibition of NF-κB or STAT3 can attenuate the tumor-cell EMT and invasiveness induced by necroptotic DAMPs." (PMID 38926796, 2024). "STAT3 increases the transcription of genes involved in the regulation of cell proliferation and survival, which leads to uncontrolled tumor growth and drug resistance." (PMID 39153914, 2024). "STAT3 is reported to inhibit the CD8+ T cells accumulation in tumor and thus inhibiting the immune response through downregulating CXCR3/CXCL10 axis." (PMID 38245798, 2024). "These cells can secrete IL-6 which, through STAT3 phosphorylation, activates the Notch pathway in tumor cells and endows them with stem cell-like properties." (PMID 38927059, 2024). "IL-6 activates Signal Transducer and Activator of Transcription 3 (STAT3), thereby facilitating tumor initiation and growth." (PMID 39683442, 2024). "This idea was corroborated by the finding that IL-10 promotes both survival and proliferation of tumor cells by stimulating STAT3 activation, at the same time hampering tumor antigen presentation to immune cells, which enhances evasion of immune surveillance." (PMID 39281678, 2024). "In CRC, exosomes from tumor cells, rich in circular RNAs, activate TAMs’ NF-κB pathway, leading to IL-6 secretion and triggering tumor cells’ Janus kinase 2 (Jak2)/STAT3 pathway." (PMID 39286635, 2024). "As a natural small molecule inhibitor of the IL-6/JAK2/STAT3 pathway, ginsenoside Rh2 shows great potential as an anti-tumor agent." (PMID 39845783, 2024).
tumor (continued). "Recent findings have emphasized the potent oncogenic function of JAK2/STAT3 signaling in tumor invasion and metastasis, emphasizing the inhibition of JAK2/STAT3 pathway as a potential therapy in malignancies." (PMID 38182570, 2024). "CMTM3 can promote the degradation of EGFR to reduce its expression, activate caspase-3 to induce cell apoptosis, and partially inhibit the JAK2/STAT3 signaling pathway to suppress tumor cell proliferation." (PMID 38223763, 2024). "In order to confirm the inhibitory effect of PPA@aPD-L1 on the NF-κB and STAT3 pathways in vivo, we detected the protein expression levels of p-p65 and p-STAT3 in tumor tissues by western blot." (PMID 39085255, 2024). "In vitro and in vivo studies illustrated that IL-1β is a key mediator of IL-6 induction via activation of the NF-κB pathway, subsequently activating the IL-6/JAK/STAT3 cascade and promoting tumor growth and aggressiveness." (PMID 38103126, 2024). "TAMs secrete large amounts of IL‐10,45, 46 which induces EMT of tumour cells through STAT3 activation and thus promotes metastasis." (PMID 38506082, 2024). "CCL2 depletion in vivo led to a decrease of phosphorylated STAT3 (pSTAT3) levels in tumor-infiltrating MDSCs." (PMID 38448555, 2024). "The production of IL-6 through this pathway activates the STAT3 pathway in tumor cells, thereby promoting tumor survival and growth." (PMID 38523155, 2024). "Evidence in a mouse model of CCA has demonstrated that M2-polarized macrophages promote tumor growth and invasiveness through IL-10/STAT3 signaling." (PMID 38730724, 2024). "This combination not only reduces cell proliferation, but also hinders metastasis by downregulating key proteins, such as vimentin and MMP9, while affecting signaling pathways, such as Akt and STAT3, to enhance tumor inhibition." (PMID 39741633, 2024). "Another example relates to the twofold repression of miR-22-3p and this tumor suppressor regulates cell growth through MET/STAT3 signaling." (PMID 38245882, 2024). "Taken together with the results of the tumor immune evaluation, PPA@aPD-L1 remolded the intratumoral immunosuppressive microenvironment by inhibiting the NF-κB and STAT3 pathways in tumor cells." (PMID 39085255, 2024). "More importantly, the NF-κB and STAT3 activation and tumor-cell EMT in peri-necroptotic microenvironment were all significantly abolished upon necroptotic-ISG15 knockdown or RAGE inhibition." (PMID 38926796, 2024). "Activation of the oncogene Stat3, which plays a critical role in tumor development, was effectively inhibited by radiotherapy in cells." (PMID 38441416, 2024). "It is known that IL-6-induced STAT3 activation promotes cell survival, tumor EMT in vitro, and is associated with elevated p-STAT3 levels in GC tissues." (PMID 38805119, 2024). "Most tumor cells overexpress IL-6, and activation of the IL-6/STAT3 signaling pathway promotes tumorigenesis by regulating multiple signaling pathways implicated in the hallmarks of cancer." (PMID 39596207, 2024). "Limiting dilution assays in nude mice revealed that the frequency of tumor-initiating cells was reduced by approximately ninefold in high STAT3 Y640F expressing cells compared to control cells." (PMID 38573819, 2024). "Constitutive STAT3 activation suppresses host anti-tumor immune responses, facilitating unregulated tumorigenesis, angiogenesis and induction of immune evasion mechanisms." (PMID 38538691, 2024). "STAT3 hyperactivation by tumor-derived growth factors is also involved in abnormal differentiation of myeloid cells into mature dendritic cells." (PMID 38339245, 2024). "Both mRNA and protein expression levels of STAT3 were statistically significantly decreased in PCa and non-tumor tissues from the Genotype-Tissue Expression Project (GTEx) and TCGA." (PMID 39132168, 2024). "Studies have also found that STAT3 mediates changes in the expression level of specific miRNAs in different tumor cells, leading to different results." (PMID 38172648, 2024).
tumor (continued). "Glioblastoma plays a crucial role in inducing the formation of an immunosuppressive phenotype in macrophages through the STAT3-mediated signaling pathway, facilitating dynamic communication between malignant tumor cells." (PMID 38195554, 2024). "The low‐risk subgroup had higher tumor mutation burden and activation of IL2/STAT5, IL2/STAT3 and IFN‐gamma response pathways." (PMID 38017652, 2024). "On the other hand, elevated STAT3 in the stromal cells of the host confers an immune-suppressed tumor microenvironment, with specific roles identified for IL-6 and IL-11." (PMID 39128004, 2024). "In the tumour microenvironment, the IL-6/STAT3 axis drives the proliferation, invasiveness, and metastasis of cancer cells, and strongly suppresses the antitumour immune response." (PMID 37950040, 2024). "Targeted STAT3 tumor immunotherapy reverses the polarization and immunosuppression of TAMs in the TME." (PMID 39372416, 2024). "Colonic tumors in cGAS-deficient mice demonstrated higher ki67 and BrdU incorporation compared to WT mice as well as increased activation of STAT3, highlighting possible effects on tumor proliferation." (PMID 39050748, 2024). "miR-21 can also cause CRC or colitis-associated cancer (CAC) by the PI3K/AKT, PDCD4/TNF-α, and IL-6/STAT3 signaling networks, activating the tumor cell invasion/metastasis process." (PMID 38542332, 2024). "Tumor-promoting cytokines such as IL-11 also induce differentiation of immunosuppression cells through activation of STAT3 signaling pathway." (PMID 38702644, 2024). "The first is that while IL-6 can lead to the activation of STAT3 in the tumor microenvironment, many other cytokines and growth factors can do so as well." (PMID 38611065, 2024). "Ultimately, further studies are needed to optimize STAT3 inhibitor activity and customize therapy based on tumor molecular profile in order to substantially expand the treatment options available to cancer patients." (PMID 38339245, 2024). "In cancer research, activated p-STAT3 has been observed to modulate B lymphocytes and facilitate tumor progression." (PMID 38935597, 2024). "Both VEGF and IL-6 possess immunosuppressive properties, facilitating immune evasion by tumor cells with excessive STAT3 activation." (PMID 38920657, 2024). "Inhibiting STAT3 signaling can promote macrophage polarization towards the M1 phenotype, which has anti-tumor properties." (PMID 38229160, 2024). "CRC-regulated macrophages regulate the EMT program and enhance migration and infiltration of CRC cells by secreting IL6, which activates the JAK2/STAT3 pathway and suppresses the tumor suppressor miR-506-3p in CRC cells." (PMID 39068459, 2024). "MiR-1301 directly targets STAT3, inhibiting cell mobility and invasion in LoVo cells (pSTAT3-positive), suggesting its role as a tumor suppressor by modulating STAT3 in CRC." (PMID 38185635, 2024). "Extensive studies from our group have demonstrated that STAT3, which is persistently activated in multiple types of immune cells in the tumor microenvironment, contributes to the suppression of IFNγ production in the tumor microenvironment." (PMID 39618825, 2024). "STAT3, an important member of the family of STATs, had been recognized as an oncogene that was closely related to tumor development." (PMID 38420199, 2024). "These activated forms of STAT3 act, in turn, as oncogenic transcription factors to promote tumor progression." (PMID 39064812, 2024). "Co-delivery of CUR and STAT3 siRNA using cationic liposomes into female C57BL/6 mice induced a significant inhibition of tumor progression after topical and intrathecal administrations." (PMID 39202863, 2024). "The pro or anti-tumorigenic effects of the IL-23/IL-23R axis are dependent upon the balance of STAT3 signaling within the tumor and the surrounding tumor cell microenvironment." (PMID 39796684, 2024).
tumor (continued). "Overexpression and aberrant activation of signal transducer and activator of transcription 3 (STAT3) contribute to tumorigenesis, drug resistance, and tumor-immune evasion, making it a potential cancer therapeutic target." (PMID 39200368, 2024). "In colon CSCs from metastatic samples, IL‐11 levels correlate with TGF‐β and SMAD2 expression in stroma, leading to STAT3 activation in tumor cells." (PMID 39309691, 2024). "Exosomes-derived from TAMs also contribute in promoting the immunosuppresive environment by transferring STAT3-targeting miRNAs (miR-21-5p and has-miR-29a-3p) to T cells and increasing the Treg/Th17 ratio and tumor progression." (PMID 38796525, 2024). "Treatment with recombinant human ISG15 induced NF-κB and STAT3 activation, tumor-cell EMT, and promoted tumor-cell migration and invasion in vitro." (PMID 38926796, 2024). "STAT3 activation in tumor-adjacent astrocytes in response to brain damage or tumor cells is well-investigated and was rapidly induced in response to intracranially injected BMCs." (PMID 38386085, 2024). "The inhibition of ERK-MAPK signaling can suppress angiogenesis and tumor growth, while targeting STAT3 can induce apoptosis and inhibit tumor cell proliferation." (PMID 38612893, 2024). "As the JAK2/p-STAT3 pathway is a classic inflammatory pathway involved in tumor progression, we subsequently explored the effects of ALKBH5 on JAK2/p-STAT3 signaling in NSCLC." (PMID 38872221, 2024). "The process primarily involves signals ignited by tumor‐derived factors, such as STAT3, Notch, NLRP3, IRF8, C/EBPβ, and so on, that are responsible for immature myeloid cell expansion without terminal differentiation." (PMID 38703051, 2024). "More recent works indicated that it interacts with and contributes to the oncogenic potential of the transcription factor STAT3 by repressing the transcription of tumor suppressor genes." (PMID 38948024, 2024). "This sustained STAT3 activation indirectly inhibits NK cell function by regulating other immune cells in the tumor microenvironment, further promoting NK cell exhaustion." (PMID 39906665, 2024). "IL-6-mediated STAT3 activity in tumor cells can stimulate the release of factors, such as VEGF and IL-10, that inhibit DC maturation." (PMID 38254801, 2024). "CpG-STAT3 siRNA, is a tumor vaccine that co-delivers CpG and STAT3 siRNA oligonucleotide, achieving a whole-body immune response and inhibiting the immune suppressive environment in TME." (PMID 38245798, 2024). "These associated anti-tumor effects are also enhanced by binding directly to Shp1, thereby promoting Shp1 phosphatase activity that involves dephosphorylating JAK kinases and STAT3 directly." (PMID 38339245, 2024). "Due to its ability to bind multiple receptors, CCL5 has been linked to multiple pathways that mediate tumor progression, including the JAK2/STAT3, NF-κB, TGFβ, PI3K/Akt, HIF-α, and Ras-ERK-MEK pathways." (PMID 39409924, 2024). "Immunohistochemical experiments detected the expression of SRPK1 downstream, β-catenin, p-JAK-2, and p-STAT3 in subcutaneous tumor tissues of nude mice." (PMID 38397980, 2024). "In tumor tissues, the phosphorylation levels of STAT3, AKT, and ERK were similar between Dnajb4+/+ and Dnajb4–/– mice, indicating universal activation of these pathways." (PMID 39738726, 2024). "It is known that the IL-6-induced JAK/STAT3 signaling pathway drives the proliferation and survival of tumor cells." (PMID 38182653, 2024). "The interaction between NF-κB and STAT3, however, is complex, as they act as cooperative partners in regulating a variety of target genes that influence tumor progression." (PMID 39493763, 2024). "An analysis of PD-L1 mRNA and protein levels revealed a positive correlation with various transcription factors (AP1, STAT3, and NFκB) in tumor samples, which led to the conclusion that JAK2-STAT3/MAPK-AP1 pathways are primary regulators of PD-L1 expression." (PMID 38786085, 2024).
tumor (continued). "cGGNBP2 encodes a protein, cGGNBP2-184aa, which forms a positive feedback loop that sustainably activates the STAT3 signaling pathway, thereby promoting tumor cell proliferation and metastasis." (PMID 39906665, 2024). "IL-6 or IL-8 secreted by tumor cells induces the activation of STAT3 in NK cells and inhibits the function of NK cells in ESCC." (PMID 38320998, 2024). "The crosstalk via STAT3 between immune and tumor cells is known to promote tumor progression by enhancing tumor cell proliferation and survival as well as immunosuppression." (PMID 39564003, 2024). "Most of them act by directly targeting tumor cells and activating STAT3-mediated signaling pathways which promote their survival." (PMID 39281678, 2024). "Among them, STAT3 plays a crucial role in tumor proliferation, differentiation, survival, immunosuppression, angiogenesis and tumorigenesis." (PMID 38303001, 2024). "The knockdown or inhibitor of STAT3 also observably suppress tumor growth in vivo, but the combination with shZDHHC20 don’t further enhance this effect." (PMID 38821916, 2024). "High expression of JAK/STAT3 proteins within both tumor and stromal cells predicts poor outcomes in CRC, and aberrant signaling is associated with distinct spatially-dependant differential gene expression." (PMID 38424636, 2024). "This therapy primarily focuses on directly and indirectly preventing the expression of STAT3 in tumor cells." (PMID 38397437, 2024). "In cancer, exogenous and endogenous inflammation lead to the activation of transcriptional regulators such as NF-κβ and STAT3 in tumor cells." (PMID 39126553, 2024). "In vitro studies and studies in murine models have demonstrated that STAT3, through the polarization of TAMs to the M2 phenotype, facilitates angiogenesis and tumor progression." (PMID 39516356, 2024). "We observed significant overexpression of JAK1 and STAT3 in tumor cells, which are pivotal members of the JAK/STAT pathway." (PMID 38191424, 2024). "Pharmacological blockade or genetic depletion of STAT3 restores an anti-tumour immune response and reduces metastatic outgrowth." (PMID 38678021, 2024). "EGFR activation is linked to excessive activation of the PD-1/PD-L1 pathway, possibly via IL-6/JAK/STAT3 pathway, resulting in an elevated likelihood of tumor immune evasion." (PMID 38541123, 2024). "Silencing FoxO3 in Foxp3GFP−creRorcfl/fl mice accelerates tumor development, accompanied by increased IL-6 and STAT3 expression within the tumor tissue." (PMID 38317142, 2024). "Among the seven members of the STAT protein family, STAT3 emerges as the most potent promoter of tumor growth and immune evasion." (PMID 38920657, 2024). "Meanwhile, the aberrant tumor-intrinsic STAT3 activation has been found to augment the resistance of HCC cells to sorafenib." (PMID 38596684, 2024). "In consequence, phosphorylated STAT3 translocates to the nucleus of tumor cells promoting the secretion of granulocyte-macrophage colony stimulating factor (GM-CSF), a cytokine that induces IL-19 synthesis in osteoclasts." (PMID 39737401, 2024). "Another pathway involved in angiogenesis is STAT3 signaling, which promotes multidirectional interactions between TAMs, ECs, and tumor cells." (PMID 39003350, 2024). "MiR-320, a tumor suppressor, targets IL-6R in CRC cells, inhibiting the IL-6R/STAT3 pathway and preventing colitis-associated CRC in mice models." (PMID 38185635, 2024). "It modulates multiple signaling pathways involved in cell cycle regulation, apoptosis, and inflammation, thereby impeding tumor growth, e.g., inhibiting cervical cancer progression to metastasis by inhibiting STAT3 phosphorylation." (PMID 39416904, 2024). "The study found that TFA can decrease the expressions of IL-6 and STAT3 via the IL-6/STAT3 pathway in Lewis ruffed tumor mice, thus suppressing tumor growth." (PMID 39215362, 2024). "As resultsshown, YY002 treatment led to the specific death of STAT3-dependentcell lines derived from various tumor types." (PMID 38559310, 2024).